FCGR2A (Fc gamma receptor IIa)
Diseases named in the same sentence as FCGR2A in open-access papers (continued):
Sharing a sentence is not in itself a finding about the gene and the disease.
ovarian carcinoma (2 papers, 2022 to 2023). A malignant neoplasm originating from the surface ovarian epithelium. "Siglec-9, the receptor of MUC16, had strong correlations with markers of neutrophil ITGAM, ITGB2, FCGR1A, FCGR2A, FCGR3A, analyzed with TCGA-OV database and ovarian cancer tissue RNA sequencing data." (PMID 37644468, 2023).
Thrombocytopenia (2 papers, 2020 to 2023). A reduction in the number of circulating thrombocytes. "A genetic study reported associations of genetic polymorphisms (the R/R genotype of FCGR2A p.R131H and the G/G genotype of CCL2 c.-2518 A > G) with thrombocytopenia; however, our study did not reveal an association of MICB and PLCE1 variants with thrombocytopenia." (PMID 37958261, 2023). "Heparin-induced thrombocytopenia in mice requires transgenic expression of human PF4 and a lack of the genetic equivalent of human Fc gamma receptor IIA (FcRIIA)." (PMID 33117353, 2020).
vasculitis (2 papers, 2019 to 2022). "The involvement of the FCGR2A gene evidences the relevant role of IgG receptors in the pathogenesis of this vasculitis, providing a biological basis for the use of intravenous immunoglobulin (IVIG), the standard treatment for KD patients." (PMID 31428096, 2019). "Moreover, several evidences, including the association observed between FCGR2A and TAK, indicate that, in addition to T lymphocytes, B cells are also involved in the pathogenesis of this vasculitis." (PMID 31428096, 2019).
acute myeloid leukemia (1 paper, 2021). Acute myeloid leukemia (AML) is a group of neoplasms arising from precursor cells committed to the myeloid cell-line differentiation. "In contrast, the expression of FCGR2A in the adrenocortical carcinoma, diffuse large B cell lymphoma, acute myeloid leukemia, pulmonary squamous carcinoma, and thymus cancer tissues was significantly lower than that of the corresponding adjacent tissues." (PMID 34285919, 2021).
Acute otitis media (1 paper, 2022). Acute otitis media is a short and generally painful infection of the middle ear. "A polymorphism within the Fcγ receptor (FCGR), FCGR2A rs1801274, is correlated with the recurrence of acute otitis media after infection with Streptococcus pneumoniae (S. pneumoniae)." (PMID 35632480, 2022).
anaphylaxis (1 paper, 2018). An acute hypersensitivity reaction that occurs from exposure to an allergen. "Four FCGR2A SNPs were identified including the previously reported intronic SNP associated with anaphylaxis, but in only 1 of 224 individuals." (PMID 30177930, 2018).
atrial fibrillation (1 paper, 2023). A disorder characterized by an electrocardiographic finding of a supraventricular arrhythmia characterized by the replacement of consistent P waves by rapid oscillations or fibrillatory waves that vary in size, shape and timing and are accompanied by an irregular ventricular response. "Recent Mendelian randomisation analysis of the blood proteome showed that increased FCGR2A levels decreased the risk of atrial fibrillation, and this receptor could be a novel drug target." (PMID 37892617, 2023).
Childhood onset (1 paper, 2021). Onset of disease at the age of between 1 and 5 years. "Besides, FCGR2A single nucleotide polymorphism conferred susceptibility to childhood-onset idiopathic nephrotic syndrome." (PMID 34285919, 2021).
Cognitive impairment (1 paper, 2025). Abnormal cognition is characterized by deficits in thinking, reasoning, or remembering. "FCGR2A‐mediated phagocytosis of synaptic components by microglia could contribute to cognitive impairment, while RASA3's role in endothelial barrier integrity may influence blood‐brain barrier disruption in SLE encephalopathy." (PMID 40958401, 2025).
Cryptococcal meningitis (1 paper, 2012). Meningeal inflammation produced by cryptococcus neoformans, an encapsulated yeast that tends to infect individuals with acquired immunodeficiency syndrome and other immunocompromised states. "In this case control genetic association study, we genotyped four functional polymorphisms in low-affinity FcγRs, including FCGR2A 131H/R, FCGR3A 158F/V, FCGR3B NA1/NA2, and FCGR2B 232I/T, in 117 patients with cryptococcal meningitis and 190 healthy controls by multiplex SNaPshot technology." (PMID 22879986, 2012). "Distribution of FCGR2A, FCGR3A, FCGR3B, FCGR2B genotypes in patients with cryptococcal meningitis and controlsa." (PMID 22879986, 2012).
Dengue hemorrhagic fever (1 paper, 2025). A serious condition caused by Dengue virus infection. "Interestingly, the FCGR2A-131R allele has been described as having a protective effect against dengue hemorrhagic fever, the most severe form of dengue infection." (PMID 40728959, 2025).
depression (1 paper, 2025). "The causal involvement of immune cells like HLA‐DR+ NK cells and genes such as FCGR2A aligns with emerging evidence of neuro‐immune crosstalk in SLE‐related depression and encephalopathy." (PMID 40958401, 2025).
follicular lymphoma (1 paper, 2013). Follicular lymphoma is a form of non-Hodgkin lymphoma characterized by a proliferation of B cells whose nodular structure of follicular architecture is preserved. "Two previous small retrospective studies of rituximab in follicular lymphoma patients also did not report any correlation between FCGR2A or 3A polymorphisms and outcome." (PMID 23286345, 2013). "The recent PRIMA study reported that FCGR2A and FCGR3A polymorphisms do not influence the response rate and outcome of follicular lymphoma patients treated with rituximab, either when it is combined with chemotherapy or used as maintenance treatment." (PMID 23286345, 2013).
HIV-1 infection (1 paper, 2019). The type species of lentivirus and the etiologic agent of acquired immunodeficiency syndrome (AIDS). "Here again, we evaluated potential associations between FCGR2A and FCGR3A variants and susceptibility to HIV-1 infection by accessing the results of a previous GWAS of HIV-1 acquisition that compared 6,300 HIV-1 infected individuals and 7,200 controls of European ancestry." (PMID 31143176, 2019).
intervertebral disc degeneration (1 paper, 2026). "Previous studies have shown that FCGR2A knockdown suppresses M1 polarization and NF-κB phosphorylation while enhancing M2 polarization and STAT3 activation in intervertebral disc degeneration models." (PMID 41602835, 2026).
kidney failure (1 paper, 2017). An acute or chronic condition that is characterized by the inability of the kidneys to adequately filter the blood. "Eight genes related to kidney toxicity, including kidney failure (CASP1, FCGR2A, FCGR2B, TLR2, TLR4, P = 0.003), damage of renal tubule (TLR2, TLR4, P = 0.01), proximal tubular toxicity (CTSS, LYZ, SLC22A5, P = 0.007) and their expression across 6 datasets were not confounded by tissue types." (PMID 28051114, 2017).
metastatic cancers (1 paper, 2021). A carcinoma which has spread from the original site of growth to another anatomic site. "FCGR2A and KLHDC8B in TEPs were positively related to metastatic cancers in comparison with healthy controls and had potential diagnostic significance for metastatic cancers with a sensitivity of 61.8%, 59.7%, and a specificity of 89.1%, 83.6%, respectively." (PMID 33955587, 2021). "Moreover, ARL2, FCGR2A, and KLHDC8B were positively associated with advanced, metastatic cancers compared to healthy controls." (PMID 33955587, 2021).
osteonecrosis (1 paper, 2023). A none disease characterized by death of bone tissue due to a lack of blood supply. "Together, these data suggested that the four key differential genes ASXL1, BNIP3L, FCGR2A and TYROBP were significantly associated with osteonecrosis of the femoral head." (PMID 36631868, 2023). "The results showed that eighteen differential genes were annotated, among which BNIP3L, ASXL1, FCGR2A and TYROBP were highly correlated with osteonecrosis." (PMID 36631868, 2023). "Through animal experiments, it was confirmed that ASXL1, BNIP3L, FCGR2A and TYROBP screened from the comparative analysis of multiple genes in the database were closely related to GIONFH, which is important for early diagnosis of Glucocorticoid-induced osteonecrosis of the femoral head." (PMID 36631868, 2023).
pulmonary diseases (1 paper, 2025). "DNA from 257 patients with various pulmonary diseases (PD) was genotyped for several GM, KM, and FCGR2A alleles, and plasma were characterized for anti-PNAG IgG antibodies." (PMID 39774260, 2025).
renal carcinoma (1 paper, 2025). A carcinoma arising from the epithelium of the renal parenchyma or the renal pelvis. "Future studies should explore longitudinal validation of this signature in diverse cohorts and assess the efficacy of FCGR2A-targeted interventions in preclinical models of metabolic dysfunction-associated renal cancer." (PMID 41199823, 2025).
renal fibrosis (1 paper, 2024). A final common manifestation of a wide variety of chronic kidney diseases characterized by glomerulosclerosis and tubulointerstitial fibrosis. "While in this study, drawing from transcriptome and single-cell sequencing data of patients with kidney fibrosis in public databases, we identified four core genes significantly associated with renal fibrosis, namely CD3G, CORO1A, FCGR2A, and GZMH." (PMID 38378674, 2024). "Through logistic analysis, tenfold cross-validation with LASSO, and gene topological analysis in Cytoscape, we pinpointed four core genes significantly associated with renal fibrosis: CD3G, CORO1A, FCGR2A, and GZMH." (PMID 38378674, 2024). "Logistic analysis, LASSO-based tenfold cross-validation, and gene topological analysis within Cytoscape identified four core genes (CD3G, CORO1A, FCGR2A, and GZMH) associated with renal fibrosis." (PMID 38378674, 2024).
respiratory infections (1 paper, 2019). "Unlike other studies, our analysis of the present LTR cohort did not reveal any significant association between FCGR2A [131R/H] and occurrence of respiratory infections or the number of infection-related deaths." (PMID 31249568, 2019).
unstable angina pectoris (1 paper, 2025). "Study reported a higher expression of FCGR2A on platelet surfaces derived from patients with AMI, unstable angina pectoris, and high-risk individuals presenting with two or more atherosclerotic risk factors." (PMID 40933471, 2025).
tumor (54 papers, 2011 to 2026). "Third, the cell-type–specific expression patterns and signaling roles of FCGR2A (e.g., in tumor-associated macrophages vs. tumor cells) warrant further investigation using single-cell and spatial transcriptomic technologies." (PMID 41208969, 2025). "Our findings shed light on the importance of FCGR2A in HNSC and contributed to the investigation on the potential relationship between FCGR2A and tumor-immune interaction and its underlying mechanism." (PMID 34285919, 2021). "In our study, the expression of FCGR2A mRNA and protein was reported to be associated with the tumor staging from grade 1 to grade 3." (PMID 34285919, 2021). "Integrating these multi-resolution datasets could clarify whether FCGR2A-driven immune modulation is predominantly immune-cell–intrinsic or tumor-cell–associated." (PMID 41208969, 2025). "Mechanistically, FCGR2A activation in tumor-associated macrophages triggers SYK-dependent PI3K phosphorylation (p-PI3K[Y607]↑2.8-fold vs controls, p=0.004), which subsequently enhances AKT-mediated lipid metabolic reprogramming through SREBP1 activation (mRNA↑3.1-fold, p=0.009)." (PMID 41199823, 2025). "The expression of FCGR2A was associated with the tumor grading, in a grade-dependent manner." (PMID 34285919, 2021). "To validate the tumor-specific expression of FCGR2A at the protein level, we performed IHC on paired HCC and adjacent tissues." (PMID 41208969, 2025). "TANs express Fc gamma receptor IIa (FcγRIIa, CD32a), enabling recognition and elimination of immunoglobulin G (IgG)-opsonised tumour cells through antigen-antibody interactions." (PMID 41451221, 2025). "Western blot (WB) analysis further confirmed this upregulation, with tumor tissues displaying a 5-fold increase in FCGR2A levels compared to adjacent liver (6.24 ± 4.28% vs. 1.20 ± 0.97%)." (PMID 41208969, 2025). "FCGR2A was predominantly localized to the membrane and cytoplasm, showing significantly higher expression in tumor tissues (p < 0.001)." (PMID 41208969, 2025). "FCGR2A can be engaged by tumor cell-derived IgG/immune complexes to facilitate platelet activation via ITAM signaling." (PMID 41226816, 2025). "Our findings position FCGR2A as a pivotal orchestrator of immune-metabolic crosstalk, bridging adipocyte-driven inflammation with tumor microenvironment remodeling through its dual roles in phagocytic signaling and Fcγ receptor-mediated myeloid activation." (PMID 41199823, 2025). "Quantification of FCGR2A protein expression revealed significant elevation in tumor tissues compared to matched normal controls (log2FC = 2.8, Wilcoxon rank-sum test p = 7.42 × 10-5)." (PMID 41199823, 2025). "Research has indicated that FCGR2A can promote antigen presentation, immune response expression, and tumour metastasis and invasion by inducing antibody‐dependent phagocytosis." (PMID 38393307, 2024). "In our study, we identified FCGR2A as a core gene to directly interact with immune landscape, promoting the activation of cell-death patterns into different anti-tumor profiles." (PMID 38237211, 2024). "The results showed that FCGR2A was significantly differentially expressed between tumor grade I and II." (PMID 37670814, 2023). "There was a noticeable correlation between the over expressions of FCGR1A/B/C, FCGR2A, and clinical cancer stages/tumor grade in ccRCC patients." (PMID 35372055, 2022). "Previous studies reported that FCGR2A regulates cancer growth, cancer invasion and has an important role in tumor recurrence." (PMID 33955587, 2021). "Paradoxically, in certain types of tumor, the expression of FCGR2A in the cancer tissues was significantly lower than the adjacent tissues." (PMID 34285919, 2021). "In summary, our study provided insights into understanding the potential role of FCGR2A in tumor immunology and its prognostic value." (PMID 34285919, 2021). "We only predicted the correlation between FCGR2A mRNA in tumor immunology and its prognostic value based on online tools." (PMID 34285919, 2021).
tumor (continued). "Furthermore, polarization of CAR‐Ms into a proinflammatory state significantly enhanced tumor‐killing efficacy, particularly in FCGR2A CAR‐Ms." (PMID 41602835, 2026). "Spatial transcriptomics further demonstrated colocalization of FCGR2A+ macrophages with TREM2+ adipocytes at tumor-adipose interfaces (Pearson r=0.76, p=2.1×10-5), suggesting direct crosstalk between obese microenvironments and immunosuppressive myeloid populations." (PMID 41199823, 2025). "Given its upstream interaction with SYK and the established downstream activation of PI3K/AKT and NF-κB signaling, it is plausible that FCGR2A may drive tumor progression through these canonical immune-related pathways." (PMID 41208969, 2025). "FCGR2A may play a role in creating an immunosuppressive tumour microenvironment and could potentially serve as a therapeutic target for HNSC." (PMID 38393307, 2024). "The results indicated that FCGR2A may activate multiple immune genes and interfere with the tumor environment in various types of cancer." (PMID 38237211, 2024). "Furthermore, using the paired-sample test analysis, we found that the expression of FCGR2A significantly differed between normal and tumor tissue." (PMID 37670814, 2023). "In addition, we investigated the correlation between FCGR2A expression and clinicopathological characteristics and tumor-infiltrating immune cells in HNSC patients." (PMID 34285919, 2021). "Moreover, we investigated the correlation between FCGR2A expression and clinicopathological characteristics or the tumor-infiltration in HNSC patients." (PMID 34285919, 2021). "In addition, high levels of HCST, C3AR1, GBP4, LY96, ANKRD22, FPR3 and FCGR2A, have also been related to immune activation and/or inflammatory response in tumours; however, their role in basal-like breast malignancies are yet to be uncovered." (PMID 28351365, 2017). "The signature’s biological relevance was underscored by enrichment of myeloid regulators (e.g., FCGR2A, AUC = 0.961) and immunoreceptor tyrosine-based activation motif (ITAM) signaling components, implicating tumor-immune crosstalk in its predictive mechanism." (PMID 41199823, 2025). "In conclusion, this study systematically delineates the role of FCGR2A in HCC immune regulation and tumor progression through multi-omics analysis, network modeling, and biological validation." (PMID 41208969, 2025). "We validated the expression pattern and biological functions of FCGR2A through IHC and in vitro assays, demonstrating its significant upregulation in HCC tissues and its capacity to promote tumor cell proliferation, migration, and invasion." (PMID 41208969, 2025). "Among these genes, FCGR2A, FYN, ITGB2, and VSIG4 protein levels were increased in tumor tissues, while MMP9 protein level was decreased, which was consistent with their mRNA expression levels." (PMID 38022584, 2023). "The expression levels of other hub genes CTLA4, CXCL10, CCL5, CCl4, ICAM1, CXCL9, CD27, GZMB, FCGR2A, SELL, IDO1 in SKCM were higher than those in non-tumor skin tissues (P < 0.05), and the results were statistically significant." (PMID 35710862, 2022). "Our findings shed light on the importance of FCGR2A in HNSC and illustrated a potential relationship between FCGR2A and tumor-immune interactions." (PMID 34285919, 2021). "Moreover, FCGR2A, presented with a higher rate of CNV amplification, was downregulated in LUAD tumor tissues, which was rarely reported." (PMID 38022584, 2023). "The results showed that the mRNA levels of FCGR1A/B/C and FCGR3A were correlated with the tumor stages of ccRCC patients, whereas the mRNA levels of FCGR2A/B/C and FCGR3B did not markedly differ among tumor stages." (PMID 35372055, 2022). "There were no statistical differences in the expression of FCGR2A among the samples obtained from cases of different gender, race, and tumor staging (P > 0.05)." (PMID 34285919, 2021).
tumor (continued). "The reason why the mRNA expression of FCGR2A/B/C and FCGR3B in ccRCC did not appear to be significantly different among tumor stages may be their unique roles in anti-tumor immunity." (PMID 35372055, 2022).